KRAS (KRas proto-oncogene, GTPase)
Diseases named in the same sentence as KRAS in open-access papers (continued):
Sharing a sentence is not in itself a finding about the gene and the disease.
tumor (continued). "A significant increase in neutrophils in the bloodstream of CRC patients harboring KRAS mutations has been shown to result in increased neutrophil mobilization and tumor site recruitment." (PMID 36707698, 2023). "Compared with KRASWT tumors, the tumor samples with KRAS mutations displayed higher expression of CD47 and p-STAT3." (PMID 36413402, 2023). "To ensure the captured cells were truly tumor cells, we performed single cell analyses, which included whole-genome amplification, followed by the detection of mutations in the KRAS, BRAF, and PIK3CA genes, which are alterations representative of CRC." (PMID 36672711, 2023). "From the cohort, we obtained data regarding age, sex, date of diagnosis, metastatic spread, KRAS status, either mutated KRAS or wild-type KRAS, and location of the primary tumor." (PMID 36788889, 2023). "The TCR-T cells are constructed and display cytokine secretion and cytotoxicity upon co-culturing with varied tumor cells expressing the KRAS-G12V mutation." (PMID 37828002, 2023). "In 2019, CRISPR/Cas9 screening was conducted to verify the function of the introduced mutant genes in the AK (APC, KRAS) mutations intestinal tumor organoid model." (PMID 37993945, 2023). "For instance, KRAS gene mutations have been linked to factors such as the patient’s sex, age, and tumor histological type." (PMID 37628934, 2023). "KRAS mutations, especially the most common mutations at codons 12 and 13, promote tumor cell metabolic reprogramming, cellular proliferation and survival." (PMID 37828002, 2023). "Upon deletion, a marked growth reduction in organoids in vitro and tumor growth in vivo revealed the ability to sensitize KRAS-mutated cancers to mTorc inhibitors, Rapamycin, and Everolimus." (PMID 37190303, 2023). "New data from the phase 1/2 CodeBreaK100 and KRYSTAL‐1 trials demonstrated that both sotorasib and adagrasib had promising anti‐tumor activity in KRAS G12C‐mutated PDAC." (PMID 36999792, 2023). "Of note, the direction of tumor progression from an initial KRAS mutation appears to dictate subsequent prognosis: median OS is 12 months vs not reached in KRAS to SMARCA4 and KRAS to EPHA3 groups, respectively." (PMID 37749078, 2023). "Surprisingly, inactivation of some of the strongest tumor suppressors in the presence of oncogenic KRAS variants decreased tumor growth in the presence of oncogenic EGFR." (PMID 37828026, 2023). "Gene set enrichment analysis (GSEA) of bulk RNA sequencing showed high stromal STAT3 tumours were characterised by enrichment of IFNγ, upregulation of KRAS signalling and inflammatory signalling Hallmark pathways." (PMID 37199043, 2023). "By analysing the phenotypic change in macrophages exposed to KRAS mutation, these researchers reported the induction of KRAS to shift macrophages towards the tumour-supporting subtype and accelerate the cancerous phenotype in the epithelium." (PMID 36835437, 2023). "The promoter region of the genomic DNA of KRAS, which is frequently mutated in tumours, also contains the G4 structure." (PMID 36855796, 2023). "The Nomogram model intuitively reveals the important contributions of ROS1 gene mutations, KRAS gene mutations, tumor staging, and endocrine system disease history to prognosis prediction." (PMID 37468609, 2023).
tumor (continued). "We demonstrated mutant KRAS had the ability to drive a reduction in cytotoxic T‐cell tumor infiltration, and thus mutated KRAS‐expressing tumors had poor response to immunotherapies." (PMID 36599679, 2023). "Tumours of colorectal cancer patients were shown to exhibit, for instance, either KRAS or NRAS mutations (referred to as RAS mutations) with a rate of about 50%, which tend to occur mutually exclusive." (PMID 37666855, 2023). "Another study detecting the circulating cell-free tumor-DNA (cft-DNA) of 29 PDAC patients showed that the survival of patients with detectable plasma KRAS mutations pre-treatment was significantly worse (16.8 months vs. not reached, p < 0.031)." (PMID 36675641, 2023). "A KRAS mutation is found in tumor cells in about 40% of patients, and around 10% of patients have a BRAS mutation." (PMID 36672489, 2023). "Patients harbouring KRAS mutations in CTCs were more likely to have poorly differentiated tumours (p = 0.039) and with lymph node metastasis (p = 0.027) and perineural invasion (p = 0.014)." (PMID 37761948, 2023). "Prior to the investigation of KRAS-mutated ctDNA in plasma, KRAS assessment was performed in tumor tissues of 61 PDAC patients using RASKET with a sensitivity of 1–5% and ddPCR with a sensitivity of 0.01–0.1%." (PMID 36959222, 2023). "We already reported on the presence of heterogeneous KRAS mutations in CTCs in patients with PDAC with often discordant mutations from the originating tumor." (PMID 37511945, 2023). "Our results reveal a direct mechanistic link between active KRAS and innate immune evasion and identify CD47 as a major effector underlying the KRAS-mediated immunosuppressive tumor microenvironment." (PMID 36413402, 2023). "T cells specific for KRAS mutants would eliminate tumor cells with KRAS mutations through secreted cytokines or via direct killing with granzyme B and perforin." (PMID 37828002, 2023). "A previous study found that KRAS mutations were associated with higher texture characteristic values (Gskewness and SDs), indicating that mutated KRAS had more tumor heterogeneity than wild-type KRAS." (PMID 37311935, 2023). "Circulating tumor DNA can be detected by targeting known tumor-specific mutations (such as KRAS and others) or looking for de novo genetic alterations by investigating multiple genes simultaneously (NGS approaches)." (PMID 37189687, 2023). "It has been found to have a synthetic lethal interaction with the mutated KRAS gene in several tumour cells." (PMID 37277696, 2023). "The analysis of tumor mutation and KRAS copy number variation revealed expressive KRAS copy number gain, well-known variants and potentially targetable variants never described before in TGCT." (PMID 37007070, 2023). "They showed that targeting KRAS oncogenic mutation decreases tumor growth in various cell lines and organoids." (PMID 37908590, 2023). "Previous work in PDAC showed that KRAS mutation engaged heterotypic fibroblasts, which subsequently instigate reciprocal signaling in tumor cells." (PMID 38097680, 2023). "Although AOM is known as a rodent colon-specific carcinogen, KRAS mutations have been detected in the neoplasia of the biliary epithelium and intrahepatic CCA." (PMID 37834032, 2023). "We show here that uPAR reinforces the MEK/ERK signaling pathway in tumor cells with a KRAS mutation with the suppression of FAK and CDC42 signaling." (PMID 36900379, 2023).
tumor (continued). "The KEGG pathway of DNA replication, the biological process of epithelial mesenchymal transition, and the hallmark gene set of KRAS signaling are known to have strong correlation to tumor progression." (PMID 37860520, 2023). "Based on these frequency calculations, a heatmap was generated reflecting the distribution of the KRAS mutation across the 2D tumor tissue surface." (PMID 37568187, 2023). "The poor prognosis outcome of patients with KRAS mutations (KRASmut) was correlated with an immunosuppressive tumor microenvironment (TME)." (PMID 36831441, 2023). "In this study, we compared the prevalence of KRAS mutations in CTCs to that of their corresponding primary tumours from patients with CRC." (PMID 37761948, 2023). "Here, we investigated the efficacy of vertical inhibition of the RAS‐pathway by targeting epidermal growth factor receptor (EGFR) and mitogen‐activated protein kinase kinase (MEK) in patient‐derived xenograft (PDX) tumours with primary KRAS mutation." (PMID 37604687, 2023). "Cancer immunotherapy that utilizes a peptide vaccine arising from epitopes of tumor-associated (TAA) or tumor-specific (TSA) neoantigens such as KRAS has the potential to modulate immune responses in a specific manner." (PMID 37240273, 2023). "One way KRAS mutation facilitated the occurrence and development of tumor was by creating an inflammatory TME23,37." (PMID 38097680, 2023). "Research has shown that patients with CRLM with a KRAS A146-mutated tumor have a higher tumor burden, associated with worse clinical outcomes, compared with patients with other KRAS mutation variants." (PMID 38067353, 2023). "Together, pharmacological inhibitors targeting the components of the ATR/CHK1/WEE1 pathway in 3 tumor entities expressing most KRAS mutations have reached phase II clinical trials." (PMID 36313934, 2023). "In this study, our objectives were to assess the interplay among age at CRC onset, tumor location, and KRAS variant status and their collective association with CRC survival time and mortality using a population-based data set." (PMID 38032636, 2023). "Comprehensive molecular profiling by NGS of the tumor progressing on BRAF/MEK inhibitors showed the appearance of a KRAS G12C mutation, which is typically mutually exclusive with BRAF mutations in LG-SCs." (PMID 36967525, 2023). "The tumor DNA screening limited the number of mutations for ctDNA analysis, and there was only knowledge of one mutation in the KRAS-positive cohort." (PMID 37434111, 2023). "This was first demonstrated in a study, which identified IL8 as a direct transcriptional target of KRAS that promoted tumor-associated inflammation and tumor progression." (PMID 37581538, 2023). "Interesting are data provided by a recent study that collected 150 enrolled patients and data concerning the preoperatory mutational status of KRAS based on the DNA of circulating tumor cells (ctDNA), studying its effect on the disease recurrence rate." (PMID 36836752, 2023). "More than 90% of PDACs harbour mutations in KRAS, and there is little discrepancy between KRAS mutations found in the tumour and in plasma." (PMID 37341038, 2023).
tumor (continued). "They demonstrated that KRAS mutation is related to good suppression of Th1 cell and cytotoxic cell immunity independently of mismatch repair status, tumor location, neoantigen load, and gene expression-based subtype." (PMID 37345083, 2023). "For each vaccine dose in the trial, all subjects will receive autologous DCs pulsed with mutant KRAS peptides corresponding to the subject’s specific tumor mutation and HLA type." (PMID 36761724, 2023). "Because LUAD, CORE and PDAC have some of the highest KRAS mutation frequencies of all solid tumors, we specifically tested the association between their K20 prediction scores and tumor characteristics." (PMID 37141389, 2023). "Another patient harboured a mutation in CTCs, but a wild-type KRAS was identified in the primary tumour." (PMID 37761948, 2023). "It is increasingly evident that KRAS mutant cancer cells not only regulate tumor-associated immune response at the level of recruitment, activation, and differentiation of immune cells, but also induce cancer cells to escape immune surveillance." (PMID 37670322, 2023). "Subsequently, others also demonstrated KRAS mutation in 100% of 33 combined tumor samples, making the prevalence of this mutation even higher than that seen in PDAC." (PMID 37538977, 2023). "Among them, 19 variants, including the KRAS p.G12D pathogenic variant, co‐existed in the original tumor and organoid." (PMID 36691316, 2023). "This analysis showed that tumors in the DLRS-low group were significantly enriched for multiple cancer hallmark-related pathways such as MYC signaling, KRAS signaling, and epithelial mesenchymal transition that are associated with aggressive tumor phenotypes." (PMID 37557177, 2023). "Treatment of live ex vivo cultured tumor cells harboring p.Gly12Val somatic mutations with anti-KRAS antibodies reduced inner plasma membrane localization of KRAS where it must tether to function." (PMID 37051535, 2023). "One was that the PIK3CA or KRAS mutation was detected in CTCs, even when the corresponding primary tumor was judged to be a wild type (Pt." (PMID 36672711, 2023). "Estimation of subdistribution hazard ratios (sHRs) for the association of KRAS status, age at onset, and tumor location with CRC CSS was conducted using the Fine and Gray competing risk model." (PMID 38032636, 2023). "The accurate prediction of key genetic mutations, such as the KRAS status, tumor staging, and extramural venous invasion (EMVI), is crucial for guiding personalized treatment decisions and improving patients’ outcomes." (PMID 38066782, 2023). "Second, we found that ROS1 gene mutations, KRAS gene mutations, tumor stage, and the endocrine system diseases history are independent prognostic factors for PD-L1 positive patients." (PMID 37468609, 2023). "Mutations or overactivation of RAS proteins, including KRAS mutations in certain cancers, can drive uncontrolled cell growth and contribute to tumour formation." (PMID 37627135, 2023). "Another approach uses liquid biopsies to monitor KRAS-mutated chromosomal instability to identify pseudoprogression and quantified circulating tumor DNA (ctDNA) has been shown to decrease in pseudoprogression compared with true progression." (PMID 37576884, 2023). "For example, the loss of HIF2α in a KRAS-driven lung tumor model surprisingly increased tumor progression, while HIF2α deficiency in mouse vascular endothelial cells reduced tumor expansion." (PMID 38173713, 2023).
tumor (continued). "Variant allele frequencies (VAFs) of KRAS mutations determined by ddPCR, reflecting tumor-derived DNA content, were compared among evDNA samples and cfDNA samples." (PMID 37708210, 2023). "One such study identified a distinct tissue and tumor-specific role for specific KRAS variants in tumor initiation and progression, emphasizing the need to model precise gene mutations observed in human cancers." (PMID 37908590, 2023). "The effect of tumour microbiota on immune evasion in KRAS-mutant tumours, and how this is linked to tumour-intrinsic signalling, is an exciting area for future investigation." (PMID 36864508, 2023). "Characterization of distinct KRAS mutation uncovered significant differences in tumor initiation and progression." (PMID 37908590, 2023). "Erastin is a small molecule that induces cancer cell death in an iron-dependent manner and its efficacy seems to be optimal in tumor cells harboring KRAS mutation, such as HEY cells." (PMID 36614279, 2023). "As in other tumours, KRAS mutations correlate with worse outcome due to the acquired resistance to epidermal growth factor receptor (EGFR) inhibitors." (PMID 37942486, 2023). "In preclinical models, combination treatment with AMG510 caused regression of KRAS-G12C-mutant tumors and improved the anti-tumor efficacy of targeted agents and chemotherapy." (PMID 37662925, 2023). "Examination of KRAS mutations was carried out by PCR on fresh tumor tissue obtained from surgery or colonoscopy." (PMID 37228916, 2023). "KRAS extinction has been shown to cause tumour regression in genetically produced KRAS-mutant cancer." (PMID 36936437, 2023). "Statistical analysis was carried out to address the associations between KRAS mutation and the patients-tumor characteristics and their prognosis on survival." (PMID 36788889, 2023). "Although digital droplet PCR (ddPCR) and NGS techniques are very sensitive, the detection of the circulating KRAS mutation imperfectly reflects the mutational load of the primary tumor from which it originates." (PMID 36765725, 2023). "KRAS-positive TNBC was associated with a favorable tumor immune milieu characterized by increased B cells and CD8+ T cells, monocytes, or M1 macrophage." (PMID 36830680, 2023). "Studying the link between tumor location and KRAS mutations in exon 4 is crucial for better characterizing CRC patients." (PMID 37628934, 2023). "The authors went on to demonstrate that combination treatment with the MEK inhibitor AZD6244 and c-MET inhibitor crizotinib led to the synergistic inhibition of KRAS-mutated CRC tumor growth in both HCT116 and SW620 xenograft mouse models." (PMID 37569406, 2023). "SOS1 inhibitors are currently being investigated in several KRAS-mutated tumor types in phase I clinical studies, both alone and in combination with other drugs." (PMID 37894382, 2023). "Remarkably, the top GA candidateis capable of delivering hard-to-deliver Cas9 ribonucleoprotein invivo, disrupting KRAS mutation in the tumor-bearingmice to inhibit tumor growth and extend their survival." (PMID 37521791, 2023). "In the mentioned dataset, authors identified only 1.7% of STK11 mutated SCLCs; noteworthy, these tumours were enriched in both KRAS (3.3%) and KEAP1 (3%) mutations, negatively affecting patients’ survival." (PMID 37240229, 2023).